RARA (retinoic acid receptor alpha)
Diseases named in the same sentence as RARA in open-access papers (continued):
Sharing a sentence is not in itself a finding about the gene and the disease.
acute promyelocytic leukemia (continued). "PML was originally found in patients who have acute promyelocytic leukemia (APL), which is caused by the fusion of PML with the retinoic acid receptor alpha (RARA) gene, which results in the expression of a chimeric protein PML-RARα." (PMID 34930370, 2021). "Promyelocytic leukemia (PML)–retinoic acid receptor alpha (RARα) is a fusion RNA found in almost 95% of acute promyelocytic leukemia (APL)." (PMID 33557176, 2021). "RARα is involved in the etiology of acute promyelocytic leukemia (APL), in which leukocyte differentiation is blocked at the promyelocyte stage." (PMID 34502048, 2021). "PML/RARα-positive blasts from acute promyelocytic leukemia (APL) patients display lower levels of miRNA let-7c than in regular promyelocytes." (PMID 33519805, 2020). "The PML/RARα fusion protein acts in concert with cooperative genetic events in the development of acute promyelocytic leukemia (APL)." (PMID 33298855, 2020). "Acute promyelocytic leukemia (APL) is a subtype of AML that is characterized by rearrangements of the RARA gene." (PMID 32900260, 2020). "The role of S100A10 in cancer was first identified in acute promyelocytic leukemia (APL), a subtype characterized by the expression of a fusion protein formed by the fusion of retinoic acid receptor alpha with promyelocytic leukemia (PML-RARα) genes." (PMID 30572596, 2018). "Among several distinctive chromosomal translocations in leukemia, PML/RARα is the most frequent translocation in acute promyelocytic leukemia (APL), which can generate one or more f-circRNAs from this fusion gene." (PMID 29349062, 2017). "Promyelocytic leukemia protein (PML) is a protein originally identified as part of a t(15:17) chromosomal translocation resulting in the fusion of PML and retinoic acid receptor alpha genes in acute promyelocytic leukemia (APL) patients (1, –, 5)." (PMID 28074026, 2017). "All-trans-retinoic acid (atRA), a biologically active form of Vitamin A and a cytodifferentiating agent is being successfully used for the treatment of acute promyelocytic leukemia (APL) in which RARα is fused to PML." (PMID 27286261, 2016). "Selective targeting of the PML/RARα oncoprotein demonstrates a successful molecular targeted therapy in acute promyelocytic leukemia (APL) with a typical t(15:17) chromosomal translocation." (PMID 27732960, 2016). "In acute promyelocytic leukemia (APL), a chromosomal translocation between the PML gene and the gene encoding the retinoic acid receptor alpha (RARα) results in the formation of a PML-RARα fusion protein that is responsible for the disease." (PMID 24656128, 2014). "The tumor suppressor promyelocytic leukemia (PML) protein is fused to the retinoic acid receptor alpha in patients suffering from acute promyelocytic leukemia (APL)." (PMID 23734343, 2013). "Acute promyelocytic leukemia (APL) is a distinct subset of acute myeloid leukemia characterized by an abnormal fusion protein promyelocytic locus gene (PML)/retinoic acid receptor α (RARA)." (PMID 23194090, 2012). "YOD1 regulates the stability of PML/RARα, CDK1, and ITCH, promoting malignant phenotypes in acute promyelocytic leukemia, triple-negative breast cancer, and hepatocellular carcinoma, respectively." (PMID 40274778, 2025). "Arsenic effectively treats acute promyelocytic leukemia by inducing SUMO and ubiquitin-dependent degradation of the promyelocytic leukemia (PML)–retinoic acid receptor alpha oncogenic fusion protein." (PMID 40239066, 2025). "In acute promyelocytic leukemia (APL), retinoid receptor function is disrupted, demonstrated by the inhibition of RARA caused by a chromosomal translocation that creates the PML/RARA fusion protein, which blocks the differentiation of myeloid cells and drives cancer cell proliferation." (PMID 41155227, 2025).
acute promyelocytic leukemia (continued). "Three cases of M3 were positive for promyelocytic leukemia and Vitamin A acid receptor alpha (PML/RARA) fusion genes, and four patients presented multiple chromosome structure and number abnormalities." (PMID 40028267, 2025). "Promyelocytic leukemia/retinoic acid receptor alpha (PML/RARA) gene translocation DNA probe revealed a fusion of PML and RARA loci in 2 of 100 interphase nuclei, confirming the anomaly in chromosome studies." (PMID 39050334, 2024). "In acute promyelocytic leukemia (APL), some rare RARA gene rearrangements exhibit resistance to ATRA and arsenic trioxide (ATO), including ZBTB16- RARA and STAT5B- RARA41." (PMID 38902322, 2024). "In principle, this is exemplified when ATRA is used to treat acute promyelocytic leukemia (PML) and target RARα within PML-RARα oncogenic fusion protein." (PMID 38928275, 2024). "A classic example is acute promyelocytic leukemia (APL), the result of a translocation that creates a retinoic acid receptor alpha (RARα) fusion gene." (PMID 37832945, 2024). "In acute promyelocytic leukemia (APL), the fusion protein PML/RARα downregulates the expression of CDKN2D by suppressing its promoter activity, which in turn affects leukemia cell proliferation and differentiation." (PMID 39422621, 2024). "In acute promyelocytic leukemia (APL), chromosomal translocation leads to the formation of a heterodimer (PML-RARα) between PML and retinoic acid receptor α (RARα)." (PMID 38383403, 2024). "Acute promyelocytic leukemia (APL), a hematological malignancy caused by PML—RARα could be successfully treated by all-trans retinoic acid and trivalent arsenic." (PMID 37686409, 2023). "In cancers, SUMOylation of promyelocytic leukemia/retinoic acid receptor alpha (PML/RARA) is important for cellular transformation and essential for the pathogenesis of acute promyelocytic leukemia." (PMID 37201027, 2023). "Differentiation therapy, i.e., all-trans retinoic acid (ATRA) and arsenic trioxide, has been shown to be an effective treatment for acute promyelocytic leukemia (APL), a distinct AML subtype characterized by the expression of the PML/RARA fusion protein." (PMID 37828578, 2023). "For example, acute promyelocytic leukemia (APL) exhibits a characteristic immunophenotype (CD34−, HLA-DR−, CD117+, CD15−) that can prompt PML::RARA gene fusion evaluation and consequent management until the molecular result is available." (PMID 37366878, 2023). "Acute promyelocytic leukemia (APL) is typically characterized by the presence of coagulopathy and the PML::RARA fusion gene." (PMID 36776354, 2022). "Studies have shown that RARα antagonizes E protein activity by inducing transcription of ID1 and ID2 in human acute promyelocytic leukemia cells treated with all-trans-retinoic acid and ID1 and ID3 gene expression in normal human keratinocytes." (PMID 35503250, 2022). "Assays have been developed for three phenotypes of particular clinical significance: NPM1, Core Bind Factor (CBF)-AML (referring to the fusions gene RUNX1::RUNX1T1 and CBFB::MYH11) and Acute Promyelocytic Leukemia (APL) (referring to the fusion gene PML::RARA)." (PMID 35892893, 2022). "Here, we assess the cell mechanics of acute promyelocytic leukemia (APL), an acute myeloid leukemia (AML) subtype characterized by a fusion gene between PML (promyelocytic leukemia protein) and RARA (retinoic acid receptor alpha)." (PMID 35141508, 2022). "However, it does not work properly in high‐risk and RA‐resistant promyelocytic leukaemia zinc finger (PLZF)‐RARα APL patients and may cause some sort of cardiovascular problems." (PMID 35946055, 2022). "These discoveries have led to ATRA being used clinically as an anti-cancer drug; combination treatments that include ATRA have been successful in inducing cancer remission, most notably with acute promyelocytic leukemia (APL), a disease marked by an RARα translocation." (PMID 35154092, 2022).
acute promyelocytic leukemia (continued). "An in vitro study demonstrated that arsenite destabilizes lysosomes, releasing proteases which act on the promyelocytic leukemia and retinoic acid receptor α (PML/RARα), a fusion protein expressed by APL cells." (PMID 34243768, 2021). "Acute promyelocytic leukemia (APL) is a subset of acute myeloid leukemia (AML) which is characterized by the fusion of promyelocytic leukemia PML and retinoic acid receptor- alpha (RAR-alpha) genes." (PMID 34140003, 2021). "A tumor-suppressive role for RNF4 was discovered in acute promyelocytic leukemia (APL), in which the oncogenic driver is a fusion protein that combines the promyelocytic leukemia protein (PML) with RARα (PML-RARα)." (PMID 34572023, 2021). "For instance, it was found that acute promyelocytic leukemia (APL), which contains the chromosomal translocation PML/RARα, can evade immune control by suppressing the PU.1-dependent activation of immunosubunits." (PMID 34206607, 2021). "For example, arsenic trioxide (As2O3, Trisenox®) has been used as standard monotherapy in acute promyelocytic leukemia (APL), which is a rare case of acute myeloid leukemia (AML), targeting the PML/RARA oncogene." (PMID 33558527, 2021). "This review focuses on cancers expressing well-known annexins, with a special emphasis on ANXA8, which is an annexin that was found to be overexpressed for the first time in acute promyelocytic leukemia (APL) carrying a fusion gene involving both PML and RARA." (PMID 32823855, 2020). "The interaction of S100A3 with RARα is observed in breast cancer and lung cancer, acute-myeloid-leukemia (AML) as well as acute promyelocytic leukemia (APL) cells, in which S100A3 binds also to PML-RARα." (PMID 30532072, 2019). "All-trans retinoic acid (ATRA) is used in the treatment of acute promyelocytic leukemia (APL), which is characterized by a chromosomal translocation involving the retinoid-receptor, RARα, resulting in the production of the PML-RARα oncogene." (PMID 30532072, 2019). "This subtype, called acute promyelocytic leukemia (APL), carries a chromosomal translocation of the gene for the retinoic acid receptor alpha (RARA)." (PMID 31508375, 2019). "Acute promyelocytic leukemia (APL) is a variety of acute myelocytic leukemia, which is mainly characterized by the chromosomal translocation of the gene of the retinoic acid receptor-alpha." (PMID 30248940, 2018). "They demonstrated that many recurrent chromosomal translocations, of PML/RARα observed in Acute Promyelocytic Leukemia (APL), MLL/AF9 in Acute Myeloid Leukemia (AML), EWSR1/FLI1 in Ewing Sarcoma and EML4/ALK1 associated with lung cancer could form f-circRNAs." (PMID 30018188, 2018). "In acute promyelocytic leukemia (APL), chromosome translocations lead to chimeric RARα proteins that result in a block in myeloid cell differentiation at the promyelocyte stage (reviewed in Ablain and de Thé 2014)." (PMID 27412076, 2017). "On the other hand, autophagy induced by ATRA and/or As2O3 contributes significantly to the degradation of oncoproteins such as PML/RARα and BCR-ABL and the regulation of therapy-induced differentiation in the case of acute promyelocytic leukemia." (PMID 28404874, 2017). "One classical example of a TFFG is the fusion between the promyelocytic leukemia (PML) gene and the transcription factor, retinoic acid receptor alpha (RARA), which is seen in 95% of acute promyelocytic leukemia (APL) patients." (PMID 29299133, 2017). "Acute promyelocytic leukemia (APL) is characterized by a balanced reciprocal translocation between chromosome 15 and 17, resulting in fusion of the promyelocytic leukemia and retinoic acid receptor alpha genes." (PMID 25805962, 2015). "In APL (Acute Promyelocytic Leukemia), differentiation of hematopoietic precursors gets blocked at promyelocytic stage due to chromosomal translocations involving Retinoic Acid Receptor alpha (RAR α) gene." (PMID 26082843, 2015).
acute promyelocytic leukemia (continued). "Retinoic acid receptor alpha (RARα) plays an essential role in the regulation of many biological processes, such as hematopoietic cell differentiation, while abnormal RARα function contributes to the pathogenesis of certain diseases including cancers, especially acute promyelocytic leukemia (APL)." (PMID 25886043, 2015). "Moreover, arsenic trioxide-induced autophagy through inhibiting the mTOR pathway contributes to degradation of the PML/RARA fusion protein in acute promyelocytic leukemia (APL)." (PMID 22829831, 2012). "The greatest success was the introduction of all-trans retinoic acid (ATRA) to treat a subtype of AML, acute promyelocytic leukemia (APL), where the retinoic acid receptor α gene (RARA) is fused to the promyelocytic leukemia gene (PML) due to a chromosomal translocation." (PMID 41369330, 2025). "Leukemic cells from transgenic mice with human chorionic gonadotropin–promyelocytic leukemia/retinoic acid receptor alpha (HCG‐PML/RARA) were transplanted into mice with nonobese diabetic severe combined immune deficiency." (PMID 40584407, 2025). "Among the retinoic acid receptors (RARα, RARβ and RARγ), the co-administration of ATRA with arsenic trioxide represents a breakthrough front-line treatment for acute promyelocytic leukemia, acting via modulation of RARα activity, offering new avenues for effectively managing the disease." (PMID 39175546, 2024). "In an in vivo experimental model of acute promyelocytic leukemia (APL), specifically the PML/RARα model, green tea was found to increase the levels of reactive oxygen species (ROS) within bone marrow Gr1+ cells, simultaneously decreasing the number of CD34+ and CD117+ cells." (PMID 37513933, 2023). "Importantly, PCR assays have been developed for three AML phenotypes: (i) acute promyelocytic leukemia (APL) (fusion gene PML::RARA); (ii) patients with NPM1 and CBF–AML (RUNX1::RUNX1T1 and CBFB::MYH11); and (iii) AML with fusion genes BCR::ABL1, KMT2::MLLT3, and DEK::NUP214." (PMID 37345204, 2023). "Some forms of acute myelogenous leukemia (AML) share typical morphological and immunophenotypic features of acute promyelocytic leukemia (APL) but are negative for promyelocytic leukemia-retinoic acid receptor alpha (PML-RARA) fusion." (PMID 36465368, 2022). "In acute promyelocytic leukemia (APL)-ascites mouse model and APL cell lines, lncRNA HOTAIRM1 facilitates formation of autophagosome to degrade oncoprotein PML nuclear body scaffold (PML)-retinoic acid receptor alpha (RARA) via targeting miR-20a." (PMID 34722769, 2021). "Some acute myeloid leukemia (AML) patients present with features mimicking the classical hypergranular subtype of acute promyelocytic leukemia (APL) but without the typical promyelocytic leukemia/retinoic acid receptor α (PML/RARα) rearrangement." (PMID 33019444, 2020). "Further recurrent genetic lesions in AML relevant for this work include lysine methyl transferase 2A (KMT2A; previously known asMLL) fusion genes, partial tandem duplications withinKMT2A (KMT2A-PTD), and fusion genes between promyelocytic leukemia and retinoic acid receptor alpha (PML-RARA)." (PMID 31723419, 2019). "The role of retinoic acid receptor α (RARα) in hematopoiesis is very important, as the fusion of RARα gene with PML gene initiates acute promyelocytic leukemia where differentiation of the myeloid lineage is blocked, followed by an uncontrolled proliferation of leukemic blasts." (PMID 28635660, 2017). "Acute promyelocytic leukemia (APL) is characterized by a balanced translocation between chromosome 17q21 and chromosome 15q22, leading to an abnormal fusion protein called promyelocytic leukemia-retinoic acid receptor alpha (PML-RARA)." (PMID 27322078, 2016). "In addition, this protein represents one of the two fusion partners in the PML/retinoic acid receptor alpha (RARA) fusion oncoprotein, which supports tumorigenesis in patients with acute promyelocytic leukemia." (PMID 21092142, 2010).
acute promyelocytic leukemia (continued). "Acute promyelocytic leukemia (APL) is a subtype of acute myeloid leukemia (AML), characterized by a fusion between the PML and RARA genes and by a block in the myeloid maturation at the promyelocytic stage." (PMID 41168841, 2025). "Acute promyelocytic leukemia (APL) is a subtype of AML, classified by a translocation between chromosomes 15 and 17 involving the PML and RARA genes and morphologically characterized by the accumulation of abnormal promyelocytes in the blood and bone marrow." (PMID 40414700, 2025). "We noted that human acute promyelocytic leukemia (APL) samples, a subtype of AML initiated by the PML::RARA fusion gene, had markedly higher expression of GAB2 than most other AMLs." (PMID 40773291, 2025). "Acute promyelocytic leukemia (APL) is a subtype of acute myeloid leukemia defined by the presence of a genetic abnormality, namely the PML::RARA gene fusion, as the result of a reciprocal balanced translocation between chromosome 17 and chromosome 15." (PMID 40095699, 2025). "All-trans retinoic acid (ATRA) is a well-established treatment for acute promyelocytic leukemia (APL), which is induced by the fusion protein PML::RARA." (PMID 39499902, 2024). "Acute promyelocytic leukemia (APL) is a subclass of AML and is characterized by a translocation of the retinoic acid receptor alpha gene located on chromosome 17." (PMID 37443789, 2023). "Rearrangements of the RARG gene, rather than of the RARA gene, have been identified in acute promyelocytic leukemia patients and involved the NUP98 (for nucleoporin, 3 patients), CPSF6 (encodes an RNA-binding protein, 4 patients), NPM1 (for nucleophosmin, 1 patient), and PML (1 patient) genes." (PMID 37569466, 2023). "From the perspective of RARα-mediated myeloid differentiation, EZH2 has been shown to play a role in a rare subtype of AML, acute promyelocytic leukemia (APL), which is generally curable with ATRA-based differentiation therapy (in contrast to non-APL AML)." (PMID 37035245, 2023). "Acute promyelocytic leukemia (APL), one of the best studied forms of AML, is characterized in ~95% of cases by the chromosomal translocation t(15:17), responsible for the generation of the PML/RARα oncoprotein and the consequent block of blasts differentiation processes." (PMID 36536122, 2023). "Acute promyelocytic leukemia (APL) is a distinct subclass of acute myeloid leukemia (AML) which is characterized by a reciprocal and balanced translocation between the promyelocytic leukemia protein (PML) gene on chromosome 15 and the retinoic acid receptor α (RARα) gene on chromosome 17." (PMID 35193533, 2022). "FIP1L1::RARA fusion could also raise the possibility of acute promyelocytic leukemia, although typical features are lacking (no increase of promyelocytes with Auer rods, no disseminated intravascular coagulation)." (PMID 35819517, 2022). "For example, chromosomal translocation involving RARA occurs in acute promyelocytic leukemia (APL), and all-trans retinoic acid (ATRA) is a highly effective and even curative therapeutic for APL patients." (PMID 34299349, 2021). "Acute promyelocytic leukemia, which is classified as AML M3, is characterized by a translocation that leads to the creation of a fusion between the PML and RARA (retinoic acid receptor) genes." (PMID 34575830, 2021). "For example, in acute promyelocytic leukemia (APL), PML/RARα appears to directly control the transcription of the immunoproteasome subunits, contributing to lowered expression of PSMB8-10 in APL cells." (PMID 32850906, 2020). "In particular, the PML/RARα translocation, which characterizes a subtype of AML referred to as acute promyelocytic leukemia (APL), produces oncogenic f-circRNAs that have been shown to favor leukemia progression in transgenic mouse models." (PMID 31024852, 2019).